INS (insulin)
Diseases named in the same sentence as INS in open-access papers (continued):
Sharing a sentence is not in itself a finding about the gene and the disease.
Obesity (continued). "In humans, VL ROCK1 activity positively correlates with glucose disposal in lean subjects, while insulin-stimulated ROCK1 activity is impaired in those with diabetes or obesity, possibly due to elevated levels of the ROCK1 antagonist RhoE." (PMID 33633690, 2020). "Mice with a myeloid-deficiency of Inhibitor of NFκB Kinase (IKK-β), NFκB's canonical activator protein, display a diminished inflammatory response in diet-induced obesity and maintain systemic insulin sensitivity." (PMID 32140136, 2020). "Prior to the IC training program, women with obesity had significantly higher levels of insulin and HOMA-IR index compared to normal-weight women." (PMID 33255278, 2020). "Several clinical and experimental researches showed that Ω-3 PUFAs have been used for improving the lipid and insulin profile in obesity and inflammation." (PMID 32928224, 2020). "After feeding high-fat-diet (HFD), accelerated obesity, attenuated insulin sensitivity, worsened fatty liver and increased acetylation of proteins in mitochondria were observed in SIRT3 KO mice." (PMID 32848876, 2020). "Hepatic steatosis, present in up to 70% of individuals with overweight and in >90% of morbidly obese ones, has been shown to perpetuate obesity and the systemic proinflammatory and insulin-resistant state." (PMID 32604889, 2020). "Remarkably, instead of enhanced JNK/p38 MAPK activity driving obesity and insulin resistance as previous studies suggested, these mice are resistant to diet-induced obesity and are insulin sensitive." (PMID 33179019, 2020). "For instance, FTO (rs17817449) is positively correlated with obesity and plasma insulin, insulin resistance, percentage body fat and fat mass in a north Indian population." (PMID 32110378, 2020). "In adipose tissue, obesity leads to infiltration of macrophages that secrete pro-inflammatory cytokines that inhibit insulin signaling by phosphorylating serine residues of IRS proteins." (PMID 32455838, 2020). "The suggested mechanism by which the resistin affects obesity and insulin homeostasis acts on target cells both via paracrine and endocrine signaling pathways and via its receptors." (PMID 33182462, 2020). "In women and adolescent girls with PCOS, obesity is a pathophysiologic principle, hence the fact that obesity leads to an increase in insulin secretion, resulting in the production of ovarian androgens." (PMID 32498675, 2020). "Global and liver-specific transgenic miR-26a mice are protected from obesity-mediated side effects, show an improved insulin sensitivity, decreased hepatic glucose production, and decreased fatty acid synthesis." (PMID 32279091, 2020). "In men with overweight/obesity, consuming an earlier dinner (17:00 vs. 21:00 h) induced greater peak insulin concentration and a trend for lower glucose incremental area under the curve in previous research." (PMID 33105701, 2020). "Growing evidence links CAP and capsinoids dietary intake to improved obesity, glucose homeostasis, and insulin sensitivity." (PMID 33276488, 2020). "Macrophage-specific deletion of IRE1α conferred resistance to high-fat diet-induced obesity, thereby linking macrophages to ER stress, inflammation and insulin sensitivity." (PMID 32180905, 2020). "The authors also emphasized that gradual progression of obesity with increased insulin secretion supports enhanced insulin to CNS and consequent regulation of weight gain." (PMID 32272767, 2020). "All of these pathways play an important role in liver insulin signaling, and all are affected by dietary-induced obesity." (PMID 32751794, 2020). "Insulin acts by binding to the insulin receptor with the downstream activation of the PI3K/Akt pathway, and dysregulation of the mediators of the insulin signaling pathway is observed in adipocytes in obesity." (PMID 32443737, 2020). "Aging, an underlying obesity phenotype, and chronicity of GWI pathology, can often lead to increased insulin levels in the blood, signifying underlying metabolic disease." (PMID 32927823, 2020).
Obesity (continued). "After the analyzed proteins were quantified by SWATH-MS, we decided to study the effect of obesity and bariatric surgery on key enzymes of de novo lipogenesis and insulin signaling." (PMID 31941045, 2020). "In recent years, leucine (Leu) has garnered considerable attention due in part to its anabolic effects on muscles and the anti-obesity effects that result from its beneficial impact on glucose tolerance, lipid metabolism, and insulin sensitivity." (PMID 32370170, 2020). "Obesity is also a key contributor to metabolic dysfunction involving impaired insulin signaling, which leads to dysfunctional glucose metabolism." (PMID 33384592, 2020). "We recently demonstrated that miR-26a promotes pancreatic cell differentiation, enhances insulin sensitivity, and prevents obesity-induced metabolic abnormalities in the liver." (PMID 32092075, 2020). "Several studies support that diets enriched with eicosapentaenoic acid (EPA) and/or docosahexaenoic acid (DHA) improve hepatic insulin sensitivity in different models of mouse obesity and metabolic syndrome." (PMID 32698439, 2020). "SCFAs supplementation with a high-fat diet improved insulin sensitivity and increased energy expenditure in a mouse model of diet-induced obesity." (PMID 32963827, 2020). "Insulin that promotes energy storing in adipose tissue is considered as the prime suspect of obesity and the target of therapy." (PMID 32272767, 2020). "A consistent positive energy balance and lack of physical activity are lifestyle factors that track closely with the rise in obesity and T2D, resulting in ectopic fat accumulation and insulin resistance in tissues such as skeletal muscle and liver." (PMID 32982968, 2020). "After 13 weeks diet, CAF-fed rats demonstrated prediabetes with significantly elevated fasting blood glucose, insulin and impaired glucose tolerance as well as obesity and dyslipidemia." (PMID 32872256, 2020). "Insulin is a known inhibitor of autophagy, and increased insulin secretion observed in obesity has a negative regulatory effect on autophagy." (PMID 32015340, 2020). "In unhealthy obesity, fat mobilization from adipocytes is impaired and insulin is unable to suppress lipolysis, which is the key mediator of increased lipid flux in ectopic organs such as liver and skeletal muscle." (PMID 32892401, 2020). "Kinase inhibition leads to a decrease in obesity and an increase in insulin sensitivity, while with the development of obesity, a pathological increase in expression is noted (rev." (PMID 33519369, 2020). "Histologically, macrophages and T cells are primarily located in the intermuscular (IMAT) or perimuscular (PMAT) adipose tissues that expand in the course of obesity, and their volume correlates with insulin resistance." (PMID 32397353, 2020). "NAMPT regulates processes related to the pathological processes of obesity and a type 2 diabetes mellitus by influencing lipid and glucose metabolism, insulin resistance, the oxidative stress response, apoptosis, and inflammation." (PMID 33414897, 2020). "Among the biochemical parameters, those that undergo the greatest changes with obesity (lipid profile, fasting glucose, insulin, etc.)are first examined." (PMID 33203044, 2020). "Indirectly, the increased insulin levels inherent to obesity lead to increased circulating oestrogen and the ensuing decrease in IGFBP1, a negative regulator of IGF1." (PMID 32069845, 2020). "Overwhelming evidence suggests that hyperuricemia is linked to obesity, hypertension, reduced HDL cholesterol, hypertriglyceridemia, hyperinsulinemia, and reduced insulin sensitivity." (PMID 33194468, 2020). "Leucine, a branched amino acid, has anti-obesity effects on glucose tolerance, lipid metabolism, and insulin sensitivity." (PMID 32370170, 2020). "To further confirm the anti-obesity effects of CO + RF in the OVX mouse model, we examined two obesity-related hormones (leptin and insulin) from the left ventricle of mice." (PMID 32019227, 2020).
Obesity (continued). "The weight loss induced by bariatric surgery can alter the expression of genes involved in insulin metabolism and obesity pathways." (PMID 32599690, 2020). "Emerging evidence has shown an important role of the microbiota–gut–brain axis in the control of food intake by the hypothalamus and in insulin and leptin signaling in the contribution to evolution of obesity." (PMID 32825073, 2020). "Dyslipidemia is frequently observed in hyperphagic obesity, particularly when the individual is insulin resistant." (PMID 32326226, 2020). "The mRNA expression of PI3K/AKT axis from 100 non-obese and obese participants with insulin sensitivity and insulin resistance states were compared in this study toward the understanding of obesity heterogeneity molecular mechanism." (PMID 32670384, 2020). "In summary, we demonstrated that administration of the gut microbe L. fermentum LM1016 ameliorated diet-induced obesity and improved metabolic biomarkers, including glucose, insulin, and leptin." (PMID 32917958, 2020). "Previous work shows that IF increases both basal and glucose-stimulated insulin secretion in mice with diet-induced obesity." (PMID 32283715, 2020). "Insulin dysregulation can probably represent a mediating mechanism in the obesity–depression relationship, strongly influenced by environmental factors." (PMID 32545890, 2020). "Serum haptoglobin levels were directly related to BMI, HOMA-IR, fasting insulin and blood glucose levels in a group of obese women, and serve as a marker of obesity." (PMID 32752277, 2020). "Blockade of TGF-β/Smad3 signaling enhances insulin sensitivity and prevents diet-induced obesity, promotes the browning of WAT with reduced levels of inflammatory cytokines and less inflammatory macrophage infiltration." (PMID 32265845, 2020). "The reduction in body weight after surgery is accompanied by a reduction in total daily insulin requirements in patients with obesity and T1DM." (PMID 33071965, 2020). "Deletion of the chemerin receptor gene (CMKLR1) showed a protective effect against obesity and decreased insulin secretion by reducing glucose uptake in skeletal muscle and adipose tissue." (PMID 32401924, 2020). "For instance, we observed correlations of the major glucose metabolism measurements such as the area under the glucose curve and insulin sensitivity with obesity-related variables such as BMI, visceral fat, and waist-to-hip ratio." (PMID 33488518, 2020). "The activities of BAT and beige cells negatively correlated with blood glucose concentration, insulin sensitivity, and obesity." (PMID 33274005, 2020). "HFD in mice increased microbial acetate production in the gut, leading to an increased vagal stimulation, promoting glucose-stimulated insulin response and increased ghrelin secretion, resulting in a pathological feedback loop of hyperphagia and obesity." (PMID 32295104, 2020). "Decreasing insulin gene expression in adult mice via partial gene ablation reversed diet-induced obesity." (PMID 32819363, 2020). "Metabolic disorders, T2DM and obesity are characterized by the impairment in the insulin secretion, sensitivity and adipose tissue function." (PMID 33746608, 2020). "Adipose tissue is one of the most affected tissues in the state of obesity and miRNAs affect adipocyte differentiation, lipogenesis and insulin sensitivity and thereby participate in the development of obesity." (PMID 32279091, 2020). "At present, the mechanisms of probiotics improving obesity are mainly related to fat metabolism, insulin sensitivity, and intestinal microbiota composition." (PMID 32218367, 2020). "For example, ablation of Siah2, a ubiquitin ligase, results in obesity and enlarged adipocytes, but preserved insulin sensitivity." (PMID 33292104, 2020).
Obesity (continued). "INSR overexpression, which occurs in human breast cancer and other epithelial tumors, independently of ER status, remarkably increases the response to circulating insulin, especially when the hormone is abnormally high, as in obesity and T2D." (PMID 32290535, 2020). "In these animals, there is central dysregulation of insulin secretion resulting in hyperinsulinemia, obesity and hyperphagia." (PMID 32326226, 2020). "Given that circulating exosomal miR-26a is reduced during obesity and can modulate insulin sensitivity in vitro, we evaluated its pathophysiological implications in vivo." (PMID 32092075, 2020). "Obesity induces AMPK dysregulation by multiple mechanisms independently of the AMP:ATP ratio including insulin resistance, inflammation, decreased adiponectin, oxidative stress and decreased activity of AMPK upstream kinase." (PMID 33396267, 2020). "Previous studies have shown that TGs and DGs were increased in obesity and T2D, and PC levels were reduced in obese or insulin-resistant subjects." (PMID 33520988, 2020). "This ABA-enriched extract, at 0.125 μg ABA/kg body weight, improves glucose tolerance, insulin sensitivity and fasting blood glucose in diet-induced obesity (DIO) and db/db mouse models." (PMID 32591558, 2020). "In the current study, we analyzed androgen in type I EC patients by multivariate logistic regression, adjusting for other positive characteristics (including insulin, estrone, and obesity factors) in a univariate analysis." (PMID 32913460, 2020). "ZDF rats showed enhanced insulin secretion after 2 weeks treatment, and with the progression of obesity, insulin secretion decreased after 6 weeks treatment." (PMID 31956333, 2020). "In this study, we define a role of intestinal microbiota in regulating insulin clearance during prolonged diet-induced obesity in mice." (PMID 32860984, 2020). "In line with this evidence, a recent clinical study reported that insulin is able to decrease the response of granulosa cells to FSH stimulation in women with obesity-related infertility during in vitro fertilization." (PMID 32681384, 2020). "In conclusion, SNPs of the DNMT3A and CARM1 genes are associated with BMD, in the latter case probably owing to a strong correlation with obesity and fasting insulin levels." (PMID 33004909, 2020). "SST and its analogues exert their effects directly in obesity through the insulin-mediated mechanism and indirectly by inducing satiety." (PMID 32272767, 2020). "Other studies have shown that high-fat-diet-induced obesity in mice exhibited lower glucose and insulin tolerance versus normal-diet mice." (PMID 31963819, 2020). "Pancreatic β-cells normally adapt to the insulin resistance of obesity by increasing insulin secretion in response to glucose and other signals." (PMID 31720686, 2020). "As insulin can bind to the IGF1 receptor, it is possible that the hyperinsulinism associated with obesity also promotes hormone-independent ER activation in the breast." (PMID 32393308, 2020). "Lastly, weight loss in obese subjects improved insulin sensitivity and reduced TNF expression in adipose tissue, suggesting a pivotal role of obesity on inflammation and insulin sensitivity." (PMID 33178196, 2020). "In fact, the release of FFAs from adipose tissue contributes, not only to declines in skeletal muscle and hepatic insulin sensitivity but also to endothelial dysfunction and reduced β-cell function in obesity, prediabetes, and T2D." (PMID 32849302, 2020). "The first evidences of obesity-mediated pro-tumorigenic activity suggested the importance of altered systemic release of signaling molecules, including insulin, IGF-1, adipokines, cytokines and sexual hormones." (PMID 32659999, 2020). "Compared with metabolically unhealthy (MU) obesity, the MH obesity phenotype has a favorable lipid profile and a normal to slightly reduced insulin sensitivity, despite similar body mass index (BMI)." (PMID 32438926, 2020).
Obesity (continued). "Paternal obesity impaired whole‐body insulin sensitivity, glucose tolerance and insulin secretion in adult rats (23–25 weeks of age)." (PMID 32539156, 2020). "These SCFAs play key functional roles in the pathophysiology of obesity by improving insulin sensitivity and glucose and lipid homeostasis, decreasing inflammation, and enhancing mucosal barrier function." (PMID 33262480, 2020). "The observed increased activity of 2h against PTP1B would make it possible for this potential allosteric site inhibitor) to enhance insulin sensitivity and thus act as an effective therapeutic for the treatment of T2D and obesity." (PMID 32156083, 2020). "Various studies have shown upregulated levels of 2-AG in both different organs and serum during obesity and hyperglycemia, which was correlated with body fat content, visceral fat mass and fasting plasma triacylglyceride and insulin concentrations." (PMID 32194509, 2020). "Insulin and leptin resistance are hallmarks of obesity, occurring following overnutrition and before the onset of major weight gain, and both are associated with mitochondrial dysfunction in the brain." (PMID 33240218, 2020). "SST analogue octreotide (OCT) alters human gastric functions such as stomach emptying and stomach volume and suppresses insulin secretion, which is beneficial in the management of obesity." (PMID 32272767, 2020). "Upon diet-induced obesity, mice with a myeloid-deficiency of IRF5 remain insulin sensitive despite increased adiposity." (PMID 32140136, 2020). "In this review, the current knowledge on S1P metabolism in regulating insulin signaling in pancreatic β cell fate and in the regulation of feeding by the hypothalamus in the context of obesity and T2D is summarized." (PMID 32668665, 2020). "Y1 receptor-specific knockout mice revealed hyperinsulinemia and increased pancreatic insulin stores, leading to the onset of obesity." (PMID 32121443, 2020). "In this line, the hypothalamus–pituitary–thyroid and insulin axes are interrelated and show impaired function in obesity." (PMID 32481623, 2020). "The insulin–insulin growth factor (IGF)-1 axis, sex hormones, and adipokines are key mediators between obesity and cancer, each of which are tightly linked to the endocrine and paracrine dysregulation of adipose tissue in obese individuals." (PMID 32471061, 2020). "The study aimed to assess insulin secretion and glucose disposal in respect to restricted (R) vs. ad libitum (Ad) feed intake for obesity development in broiler breeder hens." (PMID 33114772, 2020). "In this study, by using the phosphorylation of Akt as a marker of insulin signaling, it was possible to observe that obesity significantly reduced Akt expression in the cardiac tissue of obese mice." (PMID 32215468, 2020). "Different miRNAs are involved in the regulation of insulin signaling and blood glucose levels in T2D and participate in lipid metabolism, adipogenesis, and adipocyte differentiation in obesity." (PMID 32630452, 2020). "Pharmacological inhibition of SHP2 markedly increased glucose and insulin sensitivity in a diet-induced obesity mouse model." (PMID 32576931, 2020). "Obesity is commonly associated with an expansion of pancreatic islets and β-cells, which secrete increased quantities of insulin to compensate for obesity-induced insulin resistance." (PMID 32709161, 2020). "Based on this, we further studied the mechanism of chrysophanol-mediated obesity and fatty liver disease through its effect on thermogenesis, insulin sensitivity, glucose tolerance, and regulation of mRNA and protein expression." (PMID 33274005, 2020). "For example, skeletal muscle mass is a major responsible for glucose uptake under insulin-stimulated conditions, thereby strongly affecting insulin sensitivity, which is frequently altered in obesity." (PMID 32308541, 2020).